RAB1B (RAB1B, member RAS oncogene family)
Description:
The small GTPases Rab are key regulators of intracellular membrane trafficking, from the formation of transport vesicles to their fusion with membranes. Rabs cycle between an inactive GDP-bound form and an active GTP-bound form that is able to recruit to membranes different set of downstream effectors directly responsible for vesicle formation, movement, tethering and fusion. Plays a role in the initial events of the autophagic vacuole development which take place at specialized regions of the endoplasmic reticulum. Regulates vesicular transport between the endoplasmic reticulum and successive Golgi compartments (By similarity). Required to modulate the compacted morphology of the Golgi. Promotes the recruitment of lipid phosphatase MTMR6 to the endoplasmic reticulum-Golgi intermediate compartment (By similarity).
Tractability: Small molecule: a structure with a bound ligand is known. PROTAC: ubiquitination databases record sites on it; its protein half-life has been measured.
Gene: Protein-coding gene on chromosome 11 (66,268,590 to 66,277,492, forward strand). Ensembl gene ENSG00000174903.
Subcellular location: Cytoplasm; Membrane; Preautophagosomal structure membrane; Cytoplasm, perinuclear region
Subcellular location (Human Protein Atlas): Golgi apparatus; Endoplasmic reticulum
Pathways (Reactome):
Vesicle-mediated transport: COPI-dependent Golgi-to-ER retrograde traffic; COPI-mediated anterograde transport; COPII-mediated vesicle transport; RAB GEFs exchange GTP for GDP on RABs
Cell Cycle: Golgi Cisternae Pericentriolar Stack Reorganization
Metabolism of proteins: RAB geranylgeranylation
Gene Ontology:
Molecular function: G protein activity; GTP binding; GTPase activity; protein binding
Biological process: endoplasmic reticulum to Golgi vesicle-mediated transport; establishment of endothelial intestinal barrier; Golgi organization; positive regulation of glycoprotein metabolic process; regulation of autophagosome assembly; virion assembly; autophagosome assembly
Cellular component: cytoplasm; endoplasmic reticulum; extracellular exosome; Golgi apparatus; membrane; phagophore assembly site membrane; cytosol; endoplasmic reticulum membrane; endoplasmic reticulum-Golgi intermediate compartment membrane; Golgi membrane; transport vesicle; endoplasmic reticulum-Golgi intermediate compartment; perinuclear region of cytoplasm
Genetic constraint (gnomAD): Loss-of-function variants: 10 observed, 23.15 expected, observed/expected ratio (o/e) 0.43, 90% interval 0.26 to 0.73. The upper end of that interval is the gene's LOEUF score, 0.73, which puts it in group 3 of 6, group 1 being the genes least tolerant of losing a copy. Missense variants: 154 observed, 260.16 expected, observed/expected ratio (o/e) 0.59, 90% interval 0.52 to 0.68. Synonymous variants: 99 observed, 105.59 expected, observed/expected ratio (o/e) 0.94, 90% interval 0.8 to 1.11.
Homologues: Orthologues: chimpanzee RAB1B (100% identical), guinea pig RAB1B (100% identical), mouse Rab1b (99% identical), dog RAB1B (99% identical), rat Rab1b (98% identical), zebrafish rab1ab (94% identical), pig RAB1B (92% identical), tropical clawed frog rab1a (91% identical), zebrafish rab1aa (91% identical), rat Rab1b (87% identical). Paralogues in human: RAB1A (93% identical), RAB35 (55% identical), RAB8B (55% identical), RAB10 (53% identical), RAB8A (53% identical), RAB13 (51% identical), RAB12 (48% identical), RAB11A (48% identical), RAB11B (48% identical), RAB18 (46% identical), RAB2B (45% identical), RAB3D (45% identical), and 56 more.
Diseases named in the same sentence as RAB1B in open-access papers:
RAB1B is named in the same sentence as 27 diseases in open-access papers, as found by Europe PMC text mining. Sharing a sentence is not in itself a finding about the gene and the disease. The quoted sentences say what the papers report.
breast carcinoma (9 papers, 2015 to 2025). "TBC1D22B, a Golgi‐localized RabGAP linked to poor prognosis in breast cancer, inhibits ER‐to‐Golgi transport via RAB1B inactivation." (PMID 40878439, 2025). "NLK and DEDD are suggested to induce apoptosis and loss of RAB1B was shown to enhance the aggressiveness of breast carcinoma." (PMID 28163933, 2017). "In addition, we observed that some breast cancer samples expressed aberrantly low levels of RAB1B and that the loss of RAB1B expression in patient tissue arrays was correlated with a poor prognosis in breast cancer patients." (PMID 25970785, 2015). "Immunofluorescence staining revealed AQP1 co-localized with Rab1b in the perinuclear Golgi region of breast cancer cells." (PMID 36803413, 2023). "Our results indicated that AQP1, ANXA2, and Rab1b formed a ternary complex in the Golgi apparatus to induce breast cancer local invasion." (PMID 36803413, 2023). "Co-immunoprecipitation, immunofluorescence assays and cell functional experiments were carried out to define the relationship among AQP1, ANXA2 and Rab1b and their re-localization in breast cancer cells." (PMID 36803413, 2023). "It has been reported that reduced expression of RAB1B is correlated with poor clinical outcomes in breast cancer and colon cancer." (PMID 32710726, 2020). "Accordingly, our data show that upon RAB1B depletion in breast cancer cells, the TβR1-SMAD3 signaling pathway was activated, leading to EMT induction." (PMID 25970785, 2015). "In conclusion, using a combination of in vivo and in vitro functional metastasis assays and extensive clinical correlation analysis, we identify RAB1B as a novel tumor suppressor involved in human breast cancer." (PMID 25970785, 2015). "To evaluate the clinical importance of RAB1B in breast cancer, we performed an immunohistochemical analysis of TMAs containing samples from 250 breast cancer patients." (PMID 25970785, 2015). "In this study, by performing quantitative proteomic analyses in highly metastatic and parental breast cancer cell line, we found that RAB1B, a member of the RAS oncogene family, was significantly down-regulated in highly metastatic breast cancer cells." (PMID 25970785, 2015). "Depleting RAB1B in breast cancer cells inhibited the action of TβR1 protein ubiquitination and thereby potentiated TGF-β signaling." (PMID 25970785, 2015). "Next, we evaluated the effect of down-regulated RAB1B on the malignant phenotype of breast cancer cells in vitro." (PMID 25970785, 2015). "Furthermore, our present study discovered that AQP1 with ANXA2 and Rab1b formed a ternary complex in Golgi apparatus to induce breast cancer progression." (PMID 36803413, 2023). "However, Rab1B was also reported to be down-regulated in breast cancer and inhibits proliferation and metastasis of breast cancer cells." (PMID 28316326, 2017). "Our findings contribute novel data showing that RAB1B may serve as a novel and important biomarker to stratify patients with advanced breast cancer for more effective treatments with specific targeted therapies aimed at the TGF-β-SMAD3 pathway." (PMID 25970785, 2015). "Furthermore, in mouse models, we demonstrated that RAB1B suppressed the metastatic potential of breast cancer cells." (PMID 25970785, 2015). "Furthermore, low RAB1B expression correlated with poor prognosis in breast cancer patients." (PMID 25970785, 2015). "Importantly, RAB1B gene copy number variation is also found in many other types of cancer, such as human hepatocellular carcinomas and colon cancers, suggesting that the oncogenic role of RAB1B is not limited to breast cancer." (PMID 25970785, 2015). "Correlation analysis using 194 IDC patients or the GEPIA database indicated that AQP1 was positively correlated with ANXA2, Rab1b, CTSS, and ICAM1 in breast cancer patients." (PMID 36803413, 2023). "In this report, we demonstrate that the RAB1B-TβR1 interaction represents a critical mechanism for controlling TGF-β signaling and breast cancer cell invasion and metastasis." (PMID 25970785, 2015).
breast carcinoma (continued). "Both in vivo assay and clinical analysis data confirmed that AQP1 could induce breast cancer progression by interacting with ANXA2 and Rab1b." (PMID 36803413, 2023).
colon cancer (5 papers, 2014 to 2021). "Studies have shown that miR-502 regulates autophagy by inhibiting RAB1B, which is the key mediator of autophagy, and miR-502-5p inhibits autophagy, growth, and cell cycle progression in colon cancer cells." (PMID 33821195, 2021). "For example, hsa-miR-502-5p (miR-502) was reported to inhibit autophagy and tumor growth in colon cancer by suppression of Rab1B." (PMID 33234142, 2020). "High frequencies of copy number variation of RAB1B (9/98) were also reported in 98 human hepatocellular carcinoma tissues, and RAB1B is known to suppress colon tumor growth both in vitro and in vivo by targeting miR-502." (PMID 25970785, 2015). "In addition, ectopic expression of miR-502, which regulates Rab1B suppression, inhibits autophagy leading to colon cancer cell growth." (PMID 24801886, 2014).
lung cancer (5 papers, 2016 to 2024). A malignant neoplasm involving the lung. "Furthermore, RAB1A, a homolog of RAB1B, was proven to be upregulated in lung cancer and associated with T stage." (PMID 32710726, 2020). "On the other hand, RAB1B can be inhibited by miR‐135a and promotes cancer cell proliferation and invasion in non‐small cell lung cancer." (PMID 36606322, 2023). "Our study provided strong evidence that miR-135a was expressed at low levels in lung cancer cells and tissues, and it inhibited lung cancer cell growth, invasion and metastasis by suppressing the expression of RAB1B and multiple key components of the RAS pathway." (PMID 32710726, 2020). "However, in this study, RAB1B was shown to facilitate the proliferation and invasion of lung cancer cells, and high RAB1B expression in tumor tissues was related to poor overall survival and relapse-free survival of NSCLC patients." (PMID 32710726, 2020). "Generally, miR-135a might inhibit cancer proliferation, invasion and metastasis by downregulating RAB1B in lung cancer cells." (PMID 32710726, 2020). "Furthermore, another recent study suggested that depletion of Rab1B suppresses tumor growth by inhibiting PI3K/AKT signaling pathway in the lung cancer cell line A549." (PMID 28316326, 2017). "It would be of interest to investigate whether Rab1B, a paralog of Rab1A, could play a major role in mTOR regulation in lung cancer." (PMID 27902464, 2016). "For example, RAB1b is reported to be involved in sorafenib-resistance of HCC, and high expression of RAB26 promotes the cisplatin-based drug resistance in lung cancer." (PMID 39101146, 2024).
hepatocellular carcinoma (4 papers, 2015 to 2023). A malignant tumor that arises from hepatocytes. "Indeed, RAB1B was shown to be up-regulated in 11 hepatocellular carcinoma cases and 1 cholangiohepatoma case." (PMID 25970785, 2015). "Overexpression of RAB1A and RAB1B is found in colorectal cancer (CRC) and hepatocellular carcinoma (HCC), as well as several other cancer types including tongue squamous carcinomas (TSCCs)." (PMID 26590354, 2015). "Moreover, because increased expression of either RAB1A or RAB1B has been found in several types of cancer, including prostate cancer, hepatocellular carcinoma and colorectal carcinoma, it would be not surprising if their effects are synergistic with that of overexpressed GOLPH3." (PMID 32790781, 2020).
colorectal cancer (3 papers, 2017 to 2023). A primary or metastatic malignant neoplasm that affects the colon or rectum. "Rab1B has recently been reported to be involved in human cancer, but the role of Rab1B in colorectal cancer (CRC) remains unclear." (PMID 28316326, 2017).
triple-negative breast carcinoma (3 papers, 2015 to 2024). An invasive breast carcinoma which is negative for expression of estrogen receptor (ER), progesterone receptor (PR), and human epidermal growth factor receptor 2 (HER2). "In this work, we show, for the first time, that RAB1B is a suppressor of triple-negative breast cancer metastasis." (PMID 25970785, 2015).
nasopharyngeal carcinoma (2 papers, 2023). A carcinoma arising from the nasopharyngeal epithelium. "A long non-coding RNA, LINC00173, that is upregulated in nasopharyngeal cancer cells, could promote the growth, migration and metastasis of nasopharyngeal cancer cells by interacting with RAB1B to facilitate SDF4 secretion in a RAB1B-dependent manner." (PMID 38259614, 2023).
Alzheimer disease (1 paper, 2023). A progressive, neurodegenerative disease characterized by loss of function and death of nerve cells in several areas of the brain leading to loss of cognitive function such as memory and language. "In contrast, only Rab1A, and not Rab1B, has been associated with neurological disorders, for example, Parkinson’s disease, Alzheimer’s disease, amyotrophic lateral sclerosis, and intellectual disability." (PMID 36781179, 2023).
breast tumors (1 paper, 2015). "Because RAB1B expression varied across the breast tumor samples, we categorized RAB1B expression into low intensity and high intensity groups." (PMID 25970785, 2015). "However, RAB1B expression did not correlate with relapse-free survival in patients with luminal A, Luminal B and Her-2 positive breast tumors." (PMID 25970785, 2015).
cerebral infarction (1 paper, 2021). An ischemic condition of the brain, producing a persistent focal neurological deficit in the area of distribution of the cerebral arteries. "In vitro, the expression levels of AT1R, Ang II, Rab1a, Rab1b and VEGF in the cerebral infarction model group were significantly higher than those in the control group, with further increases after administration of FYXN drug serum." (PMID 33679398, 2021). "The results of Western blot showed that upregulating the levels of AT1R, Ang II, Rab1a, Rab1b and VEGF could promote angiogenesis, improve blood supply and alleviate cerebral infarction in MCAO animals." (PMID 33679398, 2021).
COVID-19 (1 paper, 2024). A disease caused by infection with severe acute respiratory syndrome coronavirus 2. "In contrast, SPI1 and RAB1B showed increased expression in three datasets of severe COVID-19 patients." (PMID 38262689, 2024). "Our work highlighted an increased expression of genes related to the endomembrane system, such as RAB1B, RAB24, RAB32, JAK3, and SELP, in severe COVID-19 patients’ blood samples." (PMID 38262689, 2024). "Our analysis revealed that severe COVID-19 patients exhibit overexpression of genes coding for proteins of extracellular exosomes, endomembrane system, and neutrophil granules (e.g., S100A9, LY96, and RAB1B), which may play an essential role in the cellular response to infection." (PMID 38262689, 2024).
Hepatitis (1 paper, 2023). Inflammation of the liver. "For example, it is known that the Rab1-activating protein TBC1D20 is involved in the hepatitis C, HIV-1 and HSV replication cycle and especially Rab1B plays an important role in Ebola virus particle assembly and ER-to-Golgi transport of the vesicular stomatitis virus glycoprotein." (PMID 37112806, 2023).
Legionella infection (1 paper, 2023). "During Legionella infection, Rab1b proteins are directed towards and activated at the LCV, leading to the rerouting of ER-derived vesicles to this compartment." (PMID 37076474, 2023).
malaria (1 paper, 2012). Malaria is a serious and sometimes fatal disease caused by a parasite that commonly infects a certain type of mosquito which feeds on humans. "The results showed that, compared to the negative control, the live malaria parasite was able to induce an increase in the expression of Rab1a, Rab1b, Rab7a, Rab10, Rab14, Rab20, Rab27a, Rab32 and Rab38." (PMID 22911692, 2012).
periodontitis (1 paper, 2024). An acute or chronic inflammatory process that affects the tissues that surround and support the teeth. "Spatial transcriptomics revealed significant upregulation of ACTB, GSTO1, RAB1B, HBB, DMKN, and CTSZ in basal epithelial cells during periodontitis." (PMID 39769019, 2024).
cancer (12 papers, 2014 to 2025). A tumor composed of atypical neoplastic, often pleomorphic cells that invade other tissues. "Because activation of both Rab1A and Rab1B were implicated in multiple cancer types, both should be considered when studying cancer." (PMID 36781179, 2023). "Second, Rab1A and Rab1B were implicated in multiple human diseases that range from cancer to neurodegeneration." (PMID 36781179, 2023). "RAB1B has a potential effect on cancer progression, so we constructed vectors containing the wild-type or mutant 3’-UTR of RAB1B fused directly with the downstream of the luciferase gene." (PMID 32710726, 2020). "Another recent study reported that PITPNC1 drives metastasis of multiple prevalent cancer types by enhancing Rab1B-mediated vesicular secretion of several pro-metastatic genes, which include MMP1." (PMID 28316326, 2017). "It remains to be determined whether the effects of TBC1D22B on cancer‐relevant phenotypes are exclusively determined by its inactivation of RAB1B function." (PMID 40878439, 2025). "The splice variant, sp2, would not be expected to bind RAB1B suggesting that the two splice variants function in cancer metastasis by different mechanisms." (PMID 34111527, 2021). "Some Rabs, such as Rab1b, Rab4b, Rab10, Rab22a, Rab24, and Rab25, are dysregulated in many cancers." (PMID 24587032, 2014). "Rab1A and Rab1B may be oncogenes, as they are frequently dysregulated in various human cancers." (PMID 38559361, 2023). "Further studies addressing the functional role of GOLPH3 binding to RAB1A and RAB1B will provide insights on GOLPH3 function in normal and pathological conditions such as in cancer." (PMID 32790781, 2020). "Thus, the PITPNC1/RAB1B/GOLPH3/MYO18A/F-actin module participates in anterograde traffic and in some cancers, allows malignant secretion to take place." (PMID 34111527, 2021). "Interestingly, these three genes (RAB1B, RAB2A, and RAB18) have been studied in several malignant tumors." (PMID 32432324, 2020). "To further investigate the expression and clinical significance of Rab1B and MMP9 protein in CRC, we collected 179 pairs of cancer and corresponding adjacent non-tumor tissues from CRC patients." (PMID 28316326, 2017).